MED17 (mediator complex subunit 17)
Description:
Component of the Mediator complex, a coactivator involved in the regulated transcription of nearly all RNA polymerase II-dependent genes. Mediator functions as a bridge to convey information from gene-specific regulatory proteins to the basal RNA polymerase II transcription machinery. Mediator is recruited to promoters by direct interactions with regulatory proteins and serves as a scaffold for the assembly of a functional preinitiation complex with RNA polymerase II and the general transcription factors.
Synonyms: Trap80; DRIP80; CRSP6; CRSP77; SRB4
Tractability: Small molecule: a structure with a bound ligand is known. PROTAC: ubiquitination databases record sites on it; its protein half-life has been measured.
Gene: Protein-coding gene on chromosome 11 (93,784,227 to 93,814,963, forward strand). Ensembl gene ENSG00000042429.
Subcellular location: Nucleus
Subcellular location (Human Protein Atlas): Nuclear speckles; Cytosol
Pathways (Reactome):
Gene expression (Transcription): Generic Transcription Pathway; MLL4 and MLL3 complexes regulate expression of PPARG target genes in adipogenesis and hepatic steatosis
Developmental Biology: Transcriptional regulation of white adipocyte differentiation
Disease: RSV-host interactions
Metabolism: PPARA activates gene expression
Gene Ontology:
Molecular function: nuclear thyroid hormone receptor binding; protein binding; transcription coactivator activity; transcription coregulator activity; nuclear vitamin D receptor binding; ubiquitin protein ligase activity
Biological process: positive regulation of DNA-templated transcription; positive regulation of transcription by RNA polymerase II; positive regulation of transcription initiation by RNA polymerase II; regulation of transcription by RNA polymerase II; positive regulation of transcription elongation by RNA polymerase II; RNA polymerase II preinitiation complex assembly; transcription initiation at RNA polymerase II promoter; protein ubiquitination
Cellular component: core mediator complex; mediator complex; membrane; nucleus; transcription regulator complex; nucleoplasm; ubiquitin ligase complex
Genetic constraint (gnomAD): Loss-of-function variants: 36 observed, 66.09 expected, observed/expected ratio (o/e) 0.54, 90% interval 0.42 to 0.72. The upper end of that interval is the gene's LOEUF score, 0.72, which puts it in group 2 of 6, group 1 being the genes least tolerant of losing a copy. Missense variants: 561 observed, 639.09 expected, observed/expected ratio (o/e) 0.88, 90% interval 0.82 to 0.94. Synonymous variants: 212 observed, 214.11 expected, observed/expected ratio (o/e) 0.99, 90% interval 0.88 to 1.11.
Homologues: Orthologues: guinea pig MED17 (97% identical), dog MED17 (97% identical), rat Med17 (96% identical), mouse Med17 (96% identical), macaque MED17 (96% identical), rabbit MED17 (90% identical), chimpanzee MED17 (85% identical), tropical clawed frog med17 (84% identical), pig MED17 (80% identical), zebrafish med17 (47% identical), Drosophila melanogaster MED17 (43% identical), Caenorhabditis elegans mdt-17 (22% identical).
Diseases named in the same sentence as MED17 in open-access papers:
MED17 is named in the same sentence as 14 diseases in open-access papers, as found by Europe PMC text mining. Sharing a sentence is not in itself a finding about the gene and the disease. The quoted sentences say what the papers report.
microcephaly (4 papers, 2019 to 2025). A congenital or acquired developmental disorder in which the circumference of the head is smaller than normal for the person's age and sex. "MED17 mutations lead to autosomal recessive disorders like microcephaly, intellectual disability, epilepsy, and ataxia, as evidenced by various clinical cases." (PMID 41465117, 2025). "Recessive microcephaly (postnatal progressive) with seizures and brain atrophy (MIM#613668) is due to mutations in MED17, encoding a subunit of the transcription pre-initiation mediator complex." (PMID 30755602, 2019). "MED17 was first identified in families of Caucasus Jewish origin presenting in early infancy with spasticity, profound GDD, progressive microcephaly, and epilepsy with early death, though notably without cataracts." (PMID 40745490, 2025).
dwarfism (1 paper, 2021). "The mutation in MED17, MED18, or MED20 resulted in dwarfism, delayed flowering, and reduced fertility." (PMID 33868352, 2021).
Infertility (1 paper, 2023). "Additionally, POLR2J3, MMP17, MED17, and GATAD2A are associated with various conditions ranging from infertility to neuroinflammation." (PMID 38681774, 2023). "Upregulation of genes such as POLR2J3, MMP17, and MED17 provides insights into SARS-CoV-2 pathogenesis, suggesting potential links to conditions like infertility, cancers, and neuroinflammation." (PMID 38681774, 2023).
testicular cancer (1 paper, 2016). A primary or metastatic malignant neoplasm that affects the testis. "In testicular cancer only a single overexpression (MED15) was found; while other subunits were underexpressed (MED17, MED7, MED10, MED1)." (PMID 27050271, 2016).
cancer (2 papers, 2022 to 2023). A tumor composed of atypical neoplastic, often pleomorphic cells that invade other tissues. "Then, through the signaling transmission of cascade proteins DNAH14 and CPSF4, it could enter the nucleus to downregulate TF MED17, resulting in an androgen-dependent reduction of cancer cells." (PMID 35164166, 2022).
infection (1 paper, 2025). The state of being infected such as from the introduction of a foreign agent such as serum, vaccine, antigenic substance or organism. "Meanwhile, after 2 days post-infection, Med17 overexpression (Med17-oe) led to the significant downregulation of adipogenesis-related genes, including Fasn, Scd1, Elovl6, and Lpin1 (p < 0.05)." (PMID 41199171, 2025).
MED17 also shares sentences with these, for which no sentence is quoted: developmental delay (2 papers); epilepsy (2); Brain atrophy (1); cataract (1); Cerebellar atrophy (1); Cerebral atrophy (1); Intellectual disability (1); neurological disorders (1).